CYSRT1 (cysteine rich tail 1)
Description:
Component of the stratum corneum that may contribute to epidermal antimicrobial host defenses.
Synonyms: C9orf169; MGC59937
Tractability: Antibody: its Gene Ontology location is reachable by antibodies, with high confidence.
Gene: Protein-coding gene on chromosome 9 (137,225,174 to 137,226,315, forward strand). Ensembl gene ENSG00000197191.
Subcellular location: Cornified envelope
Subcellular location (Human Protein Atlas): Nuclear speckles; Midbody; Vesicles
Gene Ontology:
Molecular function: identical protein binding; protein binding
Biological process: biological process involved in interaction with symbiont; establishment of skin barrier
Cellular component: cornified envelope; extracellular exosome
Genetic constraint (gnomAD): Loss-of-function variants: 7 observed, 5.49 expected, observed/expected ratio (o/e) 1.27, 90% interval 0.7 to 1.89. That is too few expected variants to judge how well the gene tolerates losing a copy. Missense variants: 188 observed, 193.3 expected, observed/expected ratio (o/e) 0.97, 90% interval 0.86 to 1.1. Synonymous variants: 75 observed, 79.21 expected, observed/expected ratio (o/e) 0.95, 90% interval 0.79 to 1.15.
Homologues: Orthologues: chimpanzee CYSRT1 (98% identical), macaque CYSRT1 (93% identical), mouse Cysrt1 (76% identical), dog CYSRT1 (74% identical), guinea pig CYSRT1 (73% identical), pig CYSRT1 (72% identical), rat Cysrt1 (72% identical).
Diseases named in the same sentence as CYSRT1 in open-access papers:
CYSRT1 is named in the same sentence as 6 diseases in open-access papers, as found by Europe PMC text mining. Sharing a sentence is not in itself a finding about the gene and the disease. The quoted sentences say what the papers report.
lung carcinoma (1 paper, 2025). "Although CYSRT1 has not been directly linked to lung cancer, previous studies associate it with oesophageal squamous cell cancer progression, suggesting a potential role in cancer-associated signalling pathways." (PMID 40559957, 2025).
CYSRT1 also shares sentences with these, for which no sentence is quoted: cancer (1 paper); cervical adenocarcinoma (1); cervical cancer (1); cervical squamous cell carcinoma (1); infection (1).